BRCA1 (BRCA1 DNA repair associated)
Diseases named in the same sentence as BRCA1 in open-access papers (continued):
Sharing a sentence is not in itself a finding about the gene and the disease.
pancreatic cancer (continued). "Mutations in BRCA2 confer a higher risk for developing cancers of the pancreas and male breast, and BRCA1 mutations seem to be predominantly associated with a higher risk for developing peritoneal and fallopian tube cancer." (PMID 27532258, 2016). "Larger studies are needed to further define the role of pancreatic cancer screening and the significance of abnormal imaging findings in BRCA1 and BRCA2 mutation carriers." (PMID 27069714, 2016). "We have also evaluated the contribution of BRCA1/BRCA2 founder mutations in a consecutive series of pancreatic cancers diagnosed at a tertiary cancer center." (PMID 27532258, 2016). "It has been reported that pancreatic cancer is the third most common cancer associated with BRCA1/2 mutations." (PMID 26236408, 2015). "Breast, ovarian and pancreatic cancers with BRCA1 or BRCA2 mutations and/or signature 3 mutations show larger numbers of structural rearrangements than cases without, consistent with a deficiency in error-free double-strand break repair." (PMID 26511885, 2015). "BRCA1/2 mutations are emerging as important genetic alterations in pancreatic cancer that are found in 5%–10% of patients." (PMID 26575024, 2015). "The reported relative risk to develop pancreas cancer for BRCA1 mutation carriers is 2.26 and 3.55 for BRCA2 mutation carriers." (PMID 24959366, 2014). "The BRCA1/2 defect-associated mutational signature D was relabeled ‘signature 3’ and was seen to be exclusively over-represented in breast, ovarian, and pancreatic cancers for which germline mutations to BRCA1/2 have been reported to elevate the risk." (PMID 25093514, 2014). "As previously noted, BRCA2 mutation carriers far outnumber BRCA1 mutation carriers in both HBOC-associated pancreatic cancer and FPC." (PMID 24624093, 2014). "Considering truncating mutations, the prevalence rate of our population of BRCA1/2-negative breast cancer patients with pancreatic cancer is 1.5%." (PMID 23935836, 2013). "Mutations were detected in BRCA1 and 2, which are known to play an integral role in homologous recombination repair and are frequently mutated in breast, ovarian, and pancreatic cancer." (PMID 23152778, 2012). "The incidences of prostate and pancreatic cancer for BRCA1 and BRCA2 mutation carriers were obtained by multiplying the cohort and calendar period age-specific incidence rates from the general population." (PMID 18349832, 2008). "In BRCA1 carriers pancreatic cancer risk carriers by age 70 years has been estimated to be 1.16% (95% CI 0.83–1.61%) in men, and 1.26% (95% CI 0.92–1.72%) in women, reflecting a two-fold RR." (PMID 17213823, 2007). "Pancreatic cancer is currently the only additional malignancy for which there is unequivocal evidence for increased risk in BRCA1 and BRCA2 carriers, although the absolute risk is small." (PMID 17213823, 2007). "In addition, Case 2 exhibited a deletion of the PALB2 gene and a BRCA1 (D695Y) mutation with a family history of cancer affecting four members, including one diagnosed with pancreatic cancer." (PMID 40283643, 2025). "Furthermore, in cases of TNBC with BRCA1 mutation and pancreatic cancer with BRCA2/PALB2 germline alterations, a more abundant macrophage population, encompassing M1 and M2 subtypes, is evident." (PMID 40830526, 2025). "Pancreatic cancer patients with BRCA1/BRCA2 mutations are uniquely positioned to benefit from platinum-based chemotherapies (PtCh) like FOLFIRINOX due to their tumors' defective homologous recombination repair (HRR) mechanisms, which leave them vulnerable to DNA-damaging agents." (PMID 41466916, 2025). "At a genetic level, 5–7% of pancreatic cancer patients carry germline BRCA1 or BRCA2 mutations, which may be associated with homologous recombination deficiency (HRD)." (PMID 41153346, 2025).
pancreatic cancer (continued). "In a retrospective study of 71 patients with PDAC associated with BRCA1/2, it was observed that those with unresectable pancreatic cancer treated with platinum-based agents had significantly longer overall survival (OS) compared to those who received non-platinum agents (22 vs. 9 months, p = 0.039)." (PMID 39860372, 2025). "Clinico/pathological data of pancreatic cancer patients with documented BRCA1‐2 germline pathogenic variants who had received first‐line chemotherapy for metastatic disease were collected from 23 Italian oncology departments and the impact of olaparib exposure on overall survival (OS) was analyzed." (PMID 39861955, 2025). "Indeed, BRCA1/2-deficient tumor cells are more sensitive to PARP inhibition, thus making PARP inhibition an effective treatment strategy for BRCA1/2-deficient pancreatic cancer." (PMID 39595558, 2024). "A recent study suggests that olaparib maintenance therapy could bring survival benefits to metastatic pancreatic cancer patients with germline BRCA1/2 (gBRCA1/2) mutations." (PMID 37588193, 2024). "In conclusion, our study indicated that repression of KLF5 could render BRCA1-proficient pancreatic cancer cells BRCA1 deficiency and thus sensitized them to PARP inhibition." (PMID 38433576, 2024). "In the pivotal phase 3 clinical trial of a PARP inhibitor in pancreatic cancer with germline mutations in BRCA1/2 (POLO study), the drug was to be switched from mFOLFIRINOX to Ola in cases where the tumors remained non-progressive according to RECIST after at least 4 months of mFOLFIRINOX treatment." (PMID 37956396, 2024). "Most pancreatic cancers are sporadic, but there is a small group of patients related to hereditary cancer-predisposing syndromes such as BRCA1/2 mutation, familial pancreatic cancer, Peutz-Jeghers, Lynch, Li-Fraumeni syndromes and familial atypical multiple mole melanoma." (PMID 38607041, 2024). "The purpose of this retrospective study was to identify ovarian, breast, prostate and pancreatic cancer patients who may have additional mutations and were previously only tested for BRCA1 and BRCA2 but may benefit from PARPi." (PMID 38184614, 2024). "Finally, although mutations in homologous genes BRCA1/BRCA2 increase the risk of pancreatic cancer, they also appear to be associated with better neoadjuvant efficacy, but such data is not committed in the SEER database." (PMID 38665957, 2024). "However, only 5-10% of pancreatic cancer patients have germline or somatic mutations in the BRCA1 or BRCA2 genes, which limits the application of therapies involving PARP1." (PMID 39528473, 2024). "Furthermore, it was shown that PARP inhibitors were able to induce apoptosis in pancreatic cancer cells (CAPAN-1) with mutated BRCA1/2." (PMID 38607041, 2024). "Similarly, the National Cancer Institute is also conducting a phase II trial (NCT04548752) comparing the use of Olaparib alone versus Olaparib and Pembrolizumab in metastatic germline BRCA1/2‐mutated pancreatic cancer." (PMID 36814688, 2023). "In addition, mutations in BRCA1/2 are associated with an increased lifetime risk of developing breast, ovarian, prostate, and pancreatic cancers." (PMID 38067337, 2023). "However, in this study, a previously reported BRCA1 missense variant (p.Thr293Ser) was identified in one pancreatic cancer patient and one out of 200 unaffected controls." (PMID 37951914, 2023). "In addition, the overall frequency of BRCA1/2 mutations is only approximately 10% in pancreatic cancer patients." (PMID 37415733, 2023). "One hundred and fifty unselected and prospectively enrolled pancreatic cancer patients were comprehensively screened for BRCA1/2 germline variants using denaturing high-performance liquid chromatography and high-resolution melting analyses, followed by DNA sequencing of the variant fragments." (PMID 37951914, 2023).
pancreatic cancer (continued). "It has been effective in tumors, including pancreatic cancer, with deficient homologous repair due to BRCA1/2 mutations, where DNA breaks are repaired by more error-prone pathways such as non-homologous end joining, resulting in cell cycle arrest, genetic instability, and cell death." (PMID 37179276, 2023). "A similar randomized phase II trial of maintenance olaparib in resected pancreatic cancer and pathogenic BRCA1/BRCA2 or PALB2 mutations (ECOG-ACRIN EA2192, APOLLO) is enrolling patients with either germline or somatic mutations who have received 3 to 6 months of peri-operative chemotherapy." (PMID 36975505, 2023). "Taken together, these studies suggest that BRCA1/BRCA2 mutations may serve as good predictive biomarkers for the response of pancreatic tumors to chemotherapeutic agents related to DNA damage." (PMID 37304241, 2023). "Mutations in BRCA2 also cause a 5–10% lifetime risk for pancreatic cancer, while BRCA1 carriers might have two to four times risks compared to non-carriers." (PMID 38274092, 2023). "Before pondering the potential for GC surveillance in BRCA1/2 PV carriers, it is relevant to first review the risk management recommendations for other malignancies associated with BRCA1/2 PVs, including breast, ovarian, prostate, and pancreatic cancer." (PMID 36497436, 2022). "Germline mutations in BRCA1/2 are most commonly associated with hereditary pancreatic cancer." (PMID 35163129, 2022). "Last, based on growing evidence that BRCA1/2 PVs increase risk of pancreatic cancer, guidelines have recommended pancreatic cancer surveillance with endoscopic ultrasound (EUS) or MRI for those carriers with a first- or second-degree family member with pancreatic cancer." (PMID 36497436, 2022). "PARP inhibitors are used to treat BRCA1-mutated ovarian, prostate, and pancreatic cancers." (PMID 36346676, 2022). "Genomic instability score calculated based on LOH, large-scale state transitions, and telomeric allelic imbalances was associated with sensitivity to platinum agents in a study of whole genome sequencing data of pancreatic cancer patients with pathogenic variants of BRCA1/2 or PALB2." (PMID 35163129, 2022). "Therefore, the 2019 NCCN guidelines for pancreatic cancer indicated that if the patient had a BRCA1/2 gene mutation, it was recommended to choose a platinum-containing regimen." (PMID 36387089, 2022). "Germline BRCA1/2 mutations can be found in up to 8% of patients with sporadic pancreatic cancer." (PMID 35681784, 2022). "However, even using a false discovery rate adjustment, all the observed associations for BRCA2 carriers and the pancreatic cancer association for BRCA1 carriers had false discovery rates < 0.05." (PMID 35077220, 2022). "In addition, pancreatic cancer occurred more frequently in families carrying a pathogenic BRCA1 variant along with BRCA2 c.9976A>T (double heterozygotes) (0.5) compared to wild type (0.04) and pathogenic BRCA1 carrier families (0.06)." (PMID 33672545, 2021). "Additionally, germline or somatic BRCA1/2 mutations are associated with 5−9% of the unselected cases of pancreatic cancer." (PMID 33562094, 2021). "Interestingly, pancreas cancer was also more frequent in double heterozygotes of a BRCA1 pathogenic variant and BRCA2 c.9976A>T variant, suggesting a potential genetic modifier effect." (PMID 33672545, 2021). "The c.9976A>T variant may be considered as a potential risk for lung cancer, and a potential modifying factor in pancreatic cancer when it occurs along with the pathogenic BRCA1 variant, although this observation should be validated in a larger sample cohort." (PMID 33672545, 2021). "Several prospective clinical trials have demonstrated that DNA damage-related treatment based on BRCA gene mutation may be a safe and efficient treatment for BRCA1/2-deficient pancreatic cancers." (PMID 34497764, 2021). "Similar associations between RS3/RS5 and BRCA1/2 mutations are also seen in pancreatic cancer." (PMID 34572943, 2021).
pancreatic cancer (continued). "The incidence of germline BRCA1/2 pathogenic variants in pancreatic cancer is 5%–9%." (PMID 34476650, 2021). "PVs in BRCA1/2 show high penetrance and are distributed in an autosomal-dominant pattern among carriers, resulting in a significantly elevated risk also of other malignancies, such as ovarian, prostate, melanoma, and pancreatic cancer." (PMID 34298749, 2021). "In line with this, we observed an increased proportion of pancreatic cancer prevalence in families of double heterozygotes (c.9976A>T with pathogenic BRCA1 variant), however, due to the limited number of cases, this observation should be validated in a larger sample cohort." (PMID 33672545, 2021). "Therefore, familial pancreatic cancer has a wide range of germline variants instead of a predominant gene such as BRCA1/2 in HBOC or APC in FAP." (PMID 34476650, 2021). "The effectiveness of PARP inhibitors for biliary tract cancer remains unclear, as fewer patients with BRCA1/2 germline mutations present with biliary tract cancer compared to those presenting with pancreatic cancer." (PMID 33562094, 2021). "There is also some evidence that knowledge of BRCA1 or BRCA2 mutation may direct personalized treatment of pancreatic cancer." (PMID 33920818, 2021). "Familial pancreatic cancer mutations residues are located mostly on BRCA1, BRCA2, p16, PALB2 genes." (PMID 32774122, 2020). "Inherited loss-of-function (LOF) mutations of BRCA1 confer susceptibility to breast, ovarian, prostate, and pancreatic cancer; therefore, the identification and functional assessment of BRCA1 variants is important for the clinical management of various diseases." (PMID 31467430, 2020). "A strong association between pancreatic cancer and BRCA1 and BRCA2 mutations is documented." (PMID 33198203, 2020). "In addition, there are currently 269 clinical trials registered on clinicaltrials.gov examining the use of PARP inhibitors as an anti-cancer therapy in chemo-resistant germline or somatic BRCA1/2 mutated breast, ovarian, lung, and pancreatic cancers." (PMID 33015058, 2020). "Pancreatic cancer screening can be considered for individuals with exocrine pancreatic cancer in one or more first- or second-degree relatives from the same side of the family as the identified pathogenic/likely pathogenic BRCA1/2 mutation." (PMID 32655641, 2020). "BRCA1/2 mutations have been identified in 4–7% of pancreatic cancer patients." (PMID 33015058, 2020). "Pancreatic cancers occurring in carriers of a pathogenic germline alteration in BRCA1/2 (gBRCA1/2) are assumed to demonstrate homologous recombination repair deficiency (HRD), associated with sensitivity to platinum-based chemotherapy and synthetic lethality with PARP inhibitors (PARPi)." (PMID 31787750, 2019). "Therefore, our retrospective study confirmed an increased rate of positive BRCA1/2 test in families with pancreatic cancers when associated to breast and/or ovarian tumors." (PMID 30736435, 2019). "These preclinical results indicate that DNA damaging agents are effective and could be particularly useful in the treatment of PALB2-, BRCA1- or BRCA2- deficient pancreatic tumors, which is reminiscent of human cancers defective for ‘BRCAness’." (PMID 31877165, 2019). "As shown repeatedly in both ovarian and breast cancer, the commended POLO trial has strengthened the encouragement for PARP inhibition in solid tumors, now likely setting a new standard of care in pancreatic cancer for those with germline BRCA1 or BRCA2 mutations." (PMID 32030362, 2019). "Patients with pancreatic cancer and a germline BRCA1/2 mutation have more favorable outcomes and may respond better to platinum chemotherapies and PARP inhibitors." (PMID 30186770, 2018).
pancreatic cancer (continued). "However, BRCA1/2 carriers are also at higher risk for developing gastric and pancreatic cancer and male carriers have higher prostate cancer (PC) risk." (PMID 29456621, 2018). "At the moment the very high risk groups for pancreatic cancer are still patients of AJ descent, as approximately 1.1% of the Jewish population carry a BRCA1 founder mutation and 1.1% carry a BRCA2 founder mutation, and families with ≥ 3 first- or second-degree relatives with PDAC." (PMID 29069866, 2017). "In a basket study of single-agent olaparib in patients with a germline BRCA1/2 mutation, encouraging signs of activity were observed in the subset of patients with advanced pancreatic cancer, with 5 of 23 (21.7%) obtaining an objective response to therapy and multiple patients with stable disease." (PMID 28454122, 2017). "Mutations of BRCA1 occur in approximately 6.6% of pancreatic patients and could be associated with familial pancreatic cancer risk." (PMID 28452926, 2017). "Whole-genome sequencing of 15 pancreatic cancers deliberately enriched for cases with BRCA1/2 mutations revealed the presence of signature 3 in six samples (40.0%), while examination of an unbiased set of 216 whole-exome sequenced pancreatic cancers identified signature 3 in 16 cases (∼7.41%)." (PMID 26511885, 2015). "In addition, when specifically analyzing for the BRCA1 185delAG founder mutation in pancreatic cancer patients, it was suggested that BRCA1 germline mutations do not contribute to an increased risk of pancreatic cancer." (PMID 24624093, 2014). "Indeed, carriers of BRCA2 mutations exhibit a 3.5–5.8-fold increased risk of developing pancreatic cancer compared to the general population, and mutations in the BRCA1 gene, encoding a crucial protein involved in DNA repair, are also associated with an elevated risk of pancreatic cancer." (PMID 39064499, 2024). "In addition, to determine whether BRCA1/2 gene mutations are associated with pancreatic cancer in patients with close familial relationships compared to other selection criteria." (PMID 38809921, 2024). "Approximately 7% of patients with pancreatic cancer may carry germline mutations in BRCA1/2." (PMID 36902416, 2023). "Hence, it is plausible that BRCA1/2 pathogenic variants might also be associated with pancreatic cancer risk in the Pakistani population." (PMID 37951914, 2023). "Pancreatic cancer patients with BRCA1/2 and PALB2 mutations may benefit from MMC treatment." (PMID 36359225, 2022). "Our finding in this study on the critical role of APE2 in the ATR DDR pathway in pancreatic cancer cells provides vital knowledge for future translational studies targeting APE2 functions in various mice models with different genetic backgrounds such as deficiency of ATM or BRCA1/2." (PMID 34796173, 2021). "However, the correlations between BRCA1/2 polymorphism and pancreatic cancer prognosis remained unknown." (PMID 28415599, 2017). "Additionally, BRCA1/2 mutations carriers may be more likely to die from aggressive breast or ovarian cancer at an early age, thereby masking an underlying diagnosis of pancreatic cancer." (PMID 24624093, 2014). "We further confirmed the effect of OFD1 knockdown on BRCA1 downregulation in several other pancreatic cancer cell lines (, c)." (PMID 40764600, 2025). "For instance, E2F transcription factors have been observed to upregulate RRM2 in pancreatic cancer, while BRCA1 has been demonstrated to transcriptionally activate RRM2 in glioblastoma." (PMID 40083692, 2025).